ELF3-AS1 (ELF3 antisense RNA 1)
Synonyms: ENST00000415582; SCAT7
Gene: Long non-coding RNA gene on chromosome 1 (201,995,696 to 202,010,463, reverse strand). Ensembl gene ENSG00000234678.
Diseases named in the same sentence as ELF3-AS1 in open-access papers:
ELF3-AS1 is named in the same sentence as 4 diseases in open-access papers, as found by Europe PMC text mining. Sharing a sentence is not in itself a finding about the gene and the disease. The quoted sentences say what the papers report.
hepatocellular carcinoma (1 paper, 2021). A malignant tumor that arises from hepatocytes. "Expression of long noncoding RNA (lncRNA) ELF3 antisense RNA 1 (ELF3-AS1) is observed in some cancers, while its role in hepatocellular carcinoma (HCC) is unclear." (PMID 34336727, 2021).
ELF3-AS1 also shares sentences with these, for which no sentence is quoted: cancer (4 papers); tumor (3); glioma (1).